DPRX (divergent-paired related homeobox)
Description:
Transcription factor that acts as a repressor.
Tractability: No criterion of Open Targets' tractability assessment is met for any kind of drug.
Gene: Protein-coding gene on chromosome 19 (53,600,777 to 53,637,014, forward strand). Ensembl gene ENSG00000204595.
Subcellular location: Nucleus
Gene Ontology:
Molecular function: sequence-specific double-stranded DNA binding; DNA-binding transcription factor activity, RNA polymerase II-specific; RNA polymerase II cis-regulatory region sequence-specific DNA binding; DNA binding
Biological process: regulation of transcription by RNA polymerase II; regulation of DNA-templated transcription
Cellular component: chromatin; nucleus
Genetic constraint (gnomAD): Loss-of-function variants: 12 observed, 10.39 expected, observed/expected ratio (o/e) 1.15, 90% interval 0.74 to 1.78. The upper end of that interval is the gene's LOEUF score, 1.78, which puts it in group 6 of 6, group 1 being the genes least tolerant of losing a copy. Missense variants: 211 observed, 247.87 expected, observed/expected ratio (o/e) 0.85, 90% interval 0.76 to 0.95. Synonymous variants: 72 observed, 91.21 expected, observed/expected ratio (o/e) 0.79, 90% interval 0.65 to 0.96.
Homologues: Orthologues: macaque DPRX (89% identical), pig DPRX (54% identical), dog DPRX (53% identical). Paralogues in human: OTX1 (24% identical), OTX2 (24% identical), PAX7 (23% identical), SHOX (23% identical), RAX (23% identical), DUXA (22% identical), SHOX2 (22% identical), ARX (21% identical), CRX (21% identical), PITX2 (21% identical), PITX3 (21% identical), ALX4 (21% identical), and 38 more.
Diseases named in the same sentence as DPRX in open-access papers:
DPRX is named in the same sentence as 2 diseases in open-access papers, as found by Europe PMC text mining. Sharing a sentence is not in itself a finding about the gene and the disease. The quoted sentences say what the papers report.
liver cancer (1 paper, 2026). An epithelial or non-epithelial malignant neoplasm that arises from the liver. "The identification of HBV integration near DPRX may suggest a potentially novel role for this gene in liver cancer biology, warranting further investigation into its regulatory function and contribution to oncogenesis." (PMID 41536518, 2026).
DPRX also shares sentences with these, for which no sentence is quoted: tumor (1 paper).